RN7SL422P (RNA, 7SL, cytoplasmic 422, pseudogene)
Gene: Miscellaneous RNA gene on chromosome 9 (67,175,775 to 67,176,035, reverse strand). Ensembl gene ENSG00000274852.
Homologues: Orthologues: chimpanzee Metazoa_SRP (99% identical). Paralogues in human: RN7SL343P (99% identical), RN7SL462P (99% identical), RN7SL640P (99% identical), RN7SL2 (82% identical), RN7SL3 (82% identical), RN7SL1 (81% identical), RN7SL464P (80% identical), RN7SL607P (79% identical), RN7SL597P (79% identical), RN7SL804P (79% identical), RN7SL655P (79% identical), RN7SL664P (78% identical), and 706 more.